COP1 (COP1 E3 ubiquitin ligase)
Diseases named in the same sentence as COP1 in open-access papers (continued):
Sharing a sentence is not in itself a finding about the gene and the disease.
tumor (continued). "Our human cancer sample studies indicate that COP1 is highly elevated in many types of cancer, which is in conflict with tumor suppressive role, suggesting that COP1 knockout mouse cancer studies may have some discrepancies that currently cannot be explained." (PMID 26254224, 2015). "COP1 has been confirmed as a tumor suppressor in series cancer diseases." (PMID 25884720, 2015). "The results support the hypothesis that COP1 might play a role in tumor suppression by degrading or ubiquitinating multiple substrates, besides ETV1." (PMID 25884720, 2015). "In conclusion, we demonstrated that COP1 might be a tumor suppressor by negatively regulating ETV1 in patients with TNBC." (PMID 25884720, 2015). "The COP1 KO mouse model presents a surprising discovery about its tumor suppressor role." (PMID 26254224, 2015). "Interestingly, reports suggest that COP1 exhibits both oncogenic and tumor suppressive functions depending on the cancer type." (PMID 25208737, 2014). "However, after treatment with UV and successive passages in a recovery culture, cells ectopically expressing COP1 formed a tumor of significant size in mice." (PMID 23289756, 2013). "Moreover, COP1 plays a pivotal role in the activation of PI3K/AKT pathway in tumor cells." (PMID 37025097, 2023). "Therefore, COP1 is a putative oncoprotein in CRC tumor cells." (PMID 37679762, 2023). "However, COP1 knockout mouse model studies suggest that COP1 may also behave like a tumor suppressor by mitigating the oncogenic activity of c‐Jun and ETS in some tissues." (PMID 33101846, 2020). "COP1 might be a tumor suppressor by negative regulating ETV1 in patients with TNBCs." (PMID 25884720, 2015). "To validate the role of COP1 in inhibiting ferroptosis in RCC cells in vivo, we performed a xenograft tumor model using nude mice." (PMID 40395328, 2025). "Differentially expressed genes (DEGs) in COP1 versus OP1 were identified, and Volcano plots produced with known oncogenic and tumor suppressor genes (TSG) from the OncoKB cancer gene list marked." (PMID 41331048, 2025). "Previous studies have suggested that c-Src phosphorylates ETS1, resulting in increased stabilization of ETS1 as it is not degraded by the E3 ligase COP1, leading to increased tumor progression." (PMID 40356520, 2025). "While our subcutaneous xenograft models confirmed COP1’s role in primary tumor growth and ferroptosis suppression, they do not fully address its contribution to metastasis." (PMID 40395328, 2025). "Age, tumor size and pathological types had not been found to be associated with ETV1 or COP1 expression status." (PMID 25884720, 2015).
tumor (continued). "Importantly, ectopic expression of a non-degradable UTX mutant reversed the tumor-promoting effect of COP1 overexpression." (PMID 37679762, 2023). "As COP1 is an E3 for several oncogenes and tumor suppressor proteins including c-Jun, ETS, β-Catenin, STAT3, MTA1, p27, 14-3-3σ, and C/EBPα, it is possible that it may depend on the cellular context whether high levels of COP1 are beneficial or detrimental for tumor patients." (PMID 33670160, 2021). "The ectopic expression of COP1 dramatically promoted tumorigenesis compared to parental HCT116 cells, while expression of non-degradable UTX essentially reversed the tumor-promoting effect derived from COP1 overexpression." (PMID 37679762, 2023).
cancer (45 papers, 2011 to 2026). A tumor composed of atypical neoplastic, often pleomorphic cells that invade other tissues. "Therefore, loss of COP1 expression or COP1 deficiency may be an important mechanism that leads to overexpression of ETV1 in cancer, promoting tumorigenesis." (PMID 25884720, 2015). "Studies have found that COP1 is abnormally expressed in various types of cancer, and it participates in the progression and metastasis of tumors by regulating the ubiquitination levels of key oncogenes and tumor suppressor genes." (PMID 40395328, 2025). "In our study, we identified that COP1 was the main E3 ligase responsible for c-Jun ubiquitination in drug-resistant cancer cells." (PMID 32024543, 2020). "Enhanced histone H3 acetylation of the PD-L1 promoter via the COP1/c-Jun/HDAC3 axis was crucial for the PD-L1 increase in drug-resistant cancer cells." (PMID 32024543, 2020). "In conclusion, enhanced histone H3 acetylation of the PD-L1 promoter via the COP1/c-Jun/HDAC3 axis was crucial for the PD-L1 increase in drug-resistant cancer cells." (PMID 32024543, 2020). "More studies are needed to explain these opposing results related to the function of COP1 in cancer cells." (PMID 28218667, 2017). "Our findings demonstrate that COP1 overexpression can at least partially account for p27 downregulation in many cancers." (PMID 26254224, 2015). "Further identifying the structure and functional relationship between COP1 and p27 can provide the basis for developing inhibitors that will block COP1-mediated p27 degradation and functions for rational cancer therapy." (PMID 26254224, 2015). "Significantly, we have shown that COP1 expression is positively corrected with Aurora A kinase expression in human cancer samples." (PMID 25957415, 2015). "Finally, the therapeutic potential of targeting this complex warrants deeper investigation, particularly in cancer models where COP1 activity is dysregulated." (PMID 41540009, 2026). "COP1 was upregulated in GC tissues compared with the corresponding non-carcinoma tissues." (PMID 37025097, 2023). "A better understanding of the COP1 regulatory complexity is a key to clarify its role in cancer." (PMID 33101846, 2020). "Furthermore, COP1 overexpression markedly decreased c-Jun expression in drug-resistant cancer cells." (PMID 32024543, 2020). "Therefore, COP1's physiological role in cancer remains controversial and needs further characterization." (PMID 33101846, 2020). "Our data suggest that COP1 knockout mouse cancer studies may have discrepancies that need to be resolved." (PMID 33101846, 2020). "Therefore, targeting the CSN6/COP1 or CSN6/14-3-3σ through PPI inhibition is a potential novel therapeutic strategy in targeting cancers driven by CSN6-COP1 overexpression." (PMID 33298896, 2020).
cancer (continued). "Herein, we detected that only COP1 expression was significantly decreased in all drug-resistant cancer cells in our study, which suggested the potential role of COP1 in regulating c-Jun abundance via ubiquitination in all drug-resistant cancer cells." (PMID 32024543, 2020). "Moreover, the possible role of COP1–Sox2 interaction in the development of human cancers is worthy of investigations in the future." (PMID 30405104, 2018). "However, COP1 is also a dominant E3 ubiquitin ligase for c-Jun, a proto-oncogene in several cancers, including invasive breast cancer." (PMID 28218667, 2017). "More studies are needed to determine whether targeting of COP1 or its negative regulator 14-3-3σ can have an effective therapeutic benefit in selective types of cancer." (PMID 28218667, 2017). "Another gene, RFWD2 (COP1) is a cancer suppressor and effects human β-Cell Insulin Secretion." (PMID 28117656, 2016). "We also found that COP1 overexpression is quite common in different types of cancer." (PMID 26254224, 2015). "Because CSN6 is frequently overexpressed in cancer; therefore, COP1 stabilization and its downstream impact on p27 degradation may lead to chromosomal instability." (PMID 25957415, 2015). "A better understanding of the COP1 regulatory complexity is critical for managing cancer therapy." (PMID 26254224, 2015). "Significantly, COP1 is overexpressed in many types of cancer, suggesting that tumors with COP1 overexpression may have growth advantage as shown in our cell and mouse model studies." (PMID 26254224, 2015). "Finally, whole-exome sequencing comparing mutations between formalin-fixed paraffin-embedded (FFPE) tissue biopsies, cultured CTCs, and CDX primary tumors identified both mutational concordance/discordance as well as a prospective driver, COP1, in cancer metastasis." (PMID 36980717, 2023). "Thus, the COP1-p27-Aurora kinase A link can be recapitulated in cancer samples." (PMID 25957415, 2015). "In this study, we demonstrated that COP1 is overexpressed in RCC, where it promotes cancer cell migration and invasion and correlates with poor patient prognosis." (PMID 40395328, 2025). "Further developing inhibitors that hinder EGF/CSN6/COP1‐mediated FOXO4 degradation and functions can be a strategy for rational cancer therapy." (PMID 33101846, 2020). "We found that CSN6 can link to COP1 elevation, which has unprecedented biological activity in downregulating p27, thereby inducing Aurora A; this confirms CSN6's role in promoting cancer development by influencing genome integrity." (PMID 25957415, 2015). "To substantiate the potential interaction between COP1 and ETV1, we performed cancer cell invasion assays and transwell assays using MDA-MB-231 cells." (PMID 25884720, 2015). "Overexpression of ubiquitin ligases including MDM2, COP1 and ARF-BP1 has been observed in human cancer, while downregulation of others such as FBW7 or Rnf8 promotes tumorigenesis." (PMID 22125490, 2011). "Genes like SGK1, COP1, and CDC27 promote cell proliferation and regulate apoptosis in cancer cells." (PMID 37794118, 2023). "Importantly, in these mouse xenograft cancer model studies, control tumors contain low levels of FOXO4 and COP1 while demonstrate relatively high levels of PHGDH and Glut1." (PMID 33101846, 2020).
cancer (continued). "In cancer cell lines infected with Mycobacterium bovis Bacillus Calmette–Guérin (BCG), BCG-induced Sonic Hedgehog signalling increasing COP1 expression, leading to the inhibition of apoptosis in the cell line, indicating there may be a COP1 response to mycobacterial infection." (PMID 38896446, 2024).
infection (4 papers, 2014 to 2024). The state of being infected such as from the introduction of a foreign agent such as serum, vaccine, antigenic substance or organism. "However, COP1 expression was not induced after infection, indicating that HY5, rather than COP1, was the main nematode target gene." (PMID 38992595, 2024).
neurodegenerative disease (1 paper, 2015). A disorder of the central nervous system characterized by gradual and progressive loss of neural tissue and neurologic function. "Cop-1 has been used for many years in the treatment of several neurodegenerative diseases." (PMID 25821957, 2015).
COP1 also shares sentences with these, for which no sentence is quoted: autism (3 papers); glioma (3); leukemia (3); diffuse large B-cell lymphoma (2); lymphoma (2); ovarian adenocarcinoma (2); psoriasis (2); renal cell carcinoma (2); viral infection (2); adenoma (1); Angelman syndrome (1); anthrax infection (1); Anxiety (1); Autoimmunity (1); bacterial infection (1); bone osteosarcoma (1); breast adenocarcinoma (1); cervical adenocarcinoma (1); cervical squamous cell carcinoma (1); cholangiocarcinoma (1); epilepsy (1); esophageal carcinoma (1); Fanconi anemia (1); glioblastoma (1); lung (1); lung adenocarcinoma (1); lung squamous cell carcinoma (1); lymphopenia (1); mantle cell lymphoma (1); myelodysplastic syndrome (1).
A further 10 diseases each share a sentence with COP1 in 1 paper.